CPT1B (carnitine palmitoyltransferase 1B)
Diseases named in the same sentence as CPT1B in open-access papers (continued):
Sharing a sentence is not in itself a finding about the gene and the disease.
cholesteatoma (1 paper, 2022). A pathologic process characterized by the proliferation of keratinizing squamous epithelium resulting in the accumulation of keratin and cells in the middle ear and/or mastoid. "However, in our own middle ear expression dataset from the same patients, all 12 genes were DEGs for cholesteatoma: RTN4, RAB5A, CRYBG1, RGS22, HEPHL1, and SPTLC3 were upregulated, while APBB1IP, BHLHE41, ARID3A, C5AR1, CPT1B, and FAM227A were downregulated." (PMID 36699445, 2022).
colitis (1 paper, 2025). Inflammation of the colon. "Of the WT‐enriched proteins, three were also enriched in naïve colons, including Cpt1b, Med6, and Serpina1d, while the remaining 34 upregulated proteins were only significant in the inflamed colon and may represent proteins affected by the increased legumain activity associated with colitis." (PMID 40970443, 2025).
colorectal cancer (1 paper, 2018). A primary or metastatic malignant neoplasm that affects the colon or rectum. "By using a combined approach of Microarray-Bioinformatic technologies, the authors have revealed the overexpression of CPT1B in clinical tissue specimens of colorectal cancer, demonstrating a potential metabolic mechanism contributing to colorectal cancer." (PMID 29445084, 2018).
delirium (1 paper, 2025). A disorder characterized by confusion; inattentiveness; disorientation; illusions; hallucinations; agitation; and in some instances autonomic nervous system overactivity. "There were eight protective genes (DHODH,DHRS7B,TOP1MT,CASP8,GFM1,CPT1B,TK2,GPD2), and four genes (SCP2,DMPK,GSTK1,SIRT3) that increased delirium risk, as shown inFigure 2, withp = 0.05 (dotted line); and false discovery rate (FDR) < 0.05 (red asterisks)." (PMID 41330563, 2025). "Our findings show that higher expression of 8 genes, includingDHODH,DHRS7B,TOP1MT,CASP8,GFM1,CPT1B,TK2, andGPD2, could decrease the risk of delirium." (PMID 41330563, 2025).
diabetic ketoacidosis (1 paper, 2014). The metabolic condition resulted from uncontrolled diabetes mellitus, in which the shift of acid-base status of the body toward the acid side because of loss of base or retention of acids other than carbonic acid is accompanied by the accumulation of ketone bodies in body tissues and fluids. "While we did not measure the plasma ketones, the phenotypic change of Cpt1b+/− mice is likely not due to diabetic ketoacidosis, because ketoacidosis should have caused systemic effects rather than skeletal muscle-specific insulin resistance." (PMID 25580367, 2014).
Down syndrome (1 paper, 2020). "Differential DNA methylation in CPT1B has been previously identified in blood and fetal cortex of patients with Down syndrome." (PMID 32745807, 2020). "(2016) identified a DMR in CPT1B consisting of 18 probes in Down syndrome fetal cortex samples, which spanned the region discovered in the present study." (PMID 32745807, 2020).
epilepsy (1 paper, 2022). A brain disorder characterized by episodes of abnormally increased neuronal discharge resulting in transient episodes of sensory or motor neurological dysfunction, or psychic dysfunction. "The nomogram, using RELA, PRKAB1, TNFRSF1A, CAMKK2, and CPT1B, was next confirmed as a reliable predictive model for epilepsy that would bring patients a net clinical benefit when the threshold probability ranged from 0.1 to 1.0." (PMID 36138892, 2022).
fibrosarcoma (1 paper, 2018). A malignant mesenchymal fibroblastic neoplasm affecting the soft tissue and bone. "In human UPS and fibrosarcoma CPT1A is modestly elevated or unchanged relative to normal tissues, whereas muscle-specific CPT1B is lost and FASN is increased." (PMID 30382078, 2018).
fibrosis (1 paper, 2025). the formation of excess fibrous connective tissue in an organ or tissue in a reparative or reactive process. "In mice subjected to transverse aortic constriction, AAV-mediated cardiac overexpression of CPT1B attenuated cardiomyocyte hypertrophy, cardiac fibrosis, and systolic dysfunction in vivo." (PMID 40646338, 2025).
hemorrhagic disease (1 paper, 2021). Spontaneous or near spontaneous bleeding caused by a defect in clotting mechanisms (blood coagulation disorders) or another abnormality causing a structural flaw in the blood vessels (hemostatic disorders). "Most of these genes are known to be involved in the manifestation of various clinical phenotypes, such as metabolic diseases (CPT1B and BLVRA); hemorrhagic diseases (RUNX1 and GP6); and neuronal disorders (KCNAB3, FAM179B, CCDC60, GRM6, and PRDM8), among others." (PMID 34440289, 2021).
Hyperinsulinemia (1 paper, 2014). An increased concentration of insulin in the blood. "Since the phosphorylation of IRS1 at Ser302 is substantially induced by hyperinsulinemia, the lower insulin level may also contribute to the less phosphorylation of IRS1 at Ser302 in Cpt1b+/− mouse muscle." (PMID 25309812, 2014).
lung adenocarcinoma (1 paper, 2024). A carcinoma that arises from the lung and is characterized by the presence of malignant glandular epithelial cells. "Studies have shown that in lung adenocarcinoma, CPT1B is subjected to direct transcriptional repression by the transcription factor MITF, and its high expression is able to facilitate stemness in lung adenocarcinoma cells by activating FAO." (PMID 39596847, 2024).
lung carcinoma (1 paper, 2021). "At the protein level, ALDH18A1 and CPT1B were significantly upregulated, and ACADL and PPARG were slightly underexpressed, in the lung cancer group compared to the control group, which were consistent with the results of their corresponding mRNA expressions." (PMID 34970420, 2021). "CPT1B and ACADL were the most important in the diagnosis of lung cancer in logistic regression models." (PMID 34970420, 2021). "Four differentially expressed MMRGs (ACADL, ALDH18A1, CPT1B, and PPARG) established a logistic regression model, which could effectively diagnose lung cancer." (PMID 34970420, 2021).
lung squamous cell carcinoma (1 paper, 2025). "Three compounds (gallic acid, betulinic acid, and caffeic acid) had a significant inhibitory effect on lung squamous cell carcinoma via five biolabels (CPS1, CKM, CPT1B, COX5B, and COX4I1)." (PMID 41502520, 2025).
myocardial infarction (1 paper, 2024). Gross necrosis of the myocardium, as a result of interruption of the blood supply to the area, as in coronary thrombosis. "Remarkably, reducing Mrps5 and deleting Cpt1b not only led to hyperplastic hearts, but these mutations also promoted cardiac regeneration after myocardial infarction (MI) and ischemic-reperfusion injury, respectively." (PMID 38291287, 2024).
nasopharyngeal carcinoma (1 paper, 2022). A carcinoma arising from the nasopharyngeal epithelium. "In another study, PGC-1α, the key transcription coactivator regulating CPT1A and CPT1B, binds to the transcription factor CEBPB to promote CPT1A expression, which enhances FAO activity to maintain the high NADPH/NADP+ ratio, contributing to radiation resistance of nasopharyngeal carcinoma cells." (PMID 35936710, 2022).
osteoarthritis (1 paper, 2024). A noninflammatory degenerative joint disease occurring chiefly in older persons, characterized by degeneration of the articular cartilage, hypertrophy of bone at the margins and changes in the synovial membrane. "This study highlights the potential role of Cpt1b in the regulation of muscle homeostasis in both osteoarthritis and osteoporosis, allowing for the expansion of the current knowledge of what are the molecular biological pathways involved in the regulation of muscle physiology in both diseases." (PMID 39456222, 2024). "Since Cpt1b is localized in the outer mitochondrial membrane, we next wanted to investigate the expression and potential role of Bnip3 in the muscle pathophysiology of osteoarthritis and osteoporosis." (PMID 39456222, 2024).
osteosarcoma (1 paper, 2024). A usually aggressive malignant bone-forming mesenchymal neoplasm, predominantly affecting adolescents and young adults. "The current findings align with this study, where an osteosarcoma (OS) prognostic model leveraging two genes, including CPT1B, predicted significantly poorer outcomes in the high-risk group versus the low-risk group." (PMID 38383657, 2024). "The current research corroborates the critical prognostic role of CD8+T cells in osteosarcoma (OS), as evidenced by the significant positive correlation between these immune cells and CPT1B expression." (PMID 38383657, 2024). "Dysregulation of SERPINE2 and CPT1B, along with lymphocyte imbalances, emerges as a pivotal molecular pathway in the etiology of osteosarcoma (OS)." (PMID 38383657, 2024). "In our study, the prognostic model identified certain genes, notably SERPINE2 and CPT1B, as having a strong correlation with the prognosis of osteosarcoma (OS)." (PMID 38383657, 2024). "Our investigation into osteosarcoma (OS) prognosis concerning apoptosis-related genes found that high SERPINE2 and CPT1B expression correlates with poor survival." (PMID 38383657, 2024).
Sepsis (1 paper, 2025). Sepsis is defined as life-threatening organ dysfunction caused by a dysregulated host response to infection. "Gene expression of CPT-1b (Cpt1b), responsible for the mitochondrial uptake of fatty-acyl-CoA was not affected, whereas expression of the dehydrogenase enzymes (Acadm, Acadl), required for the conversion to acetyl-CoA, were downregulated in prolonged sepsis." (PMID 39821755, 2025).
Shock (1 paper, 2026). The state in which profound and widespread reduction of effective tissue perfusion leads first to reversible, and then if prolonged, to irreversible cellular injury. "Crotonylproteomic analysis was subsequently performed on myocardial tissues to profile the Kcr modifications that occurred during endotoxic shock, and we found that the Kcr of carnitine palmitoyltransferase 1B (CPT1B) at the K321 site was significantly upregulated in LPS-treated rats." (PMID 42209697, 2026).
Stillbirth (1 paper, 2023). Death of the fetus in utero after at least 22 weeks of gestation. "Therefore, we were unable to test for associations of placental CPT1B expression with adverse pregnancy outcomes such as pre-eclampsia and stillbirth that are linked with placental dysfunction and advanced maternal age." (PMID 37275238, 2023).
cancer (28 papers, 2016 to 2026). A tumor composed of atypical neoplastic, often pleomorphic cells that invade other tissues. "We also observed significantly decreased levels of GLUT4, GCK, CD36 and CPT1b for most of the UCP1-CRISPRa co-cultured cancer organoids, suggesting that they have lower glycolysis and fatty acid metabolism." (PMID 39905264, 2025). "As MT1G levels increased, CPT1B levels progressively decreased in different grades of ccRCC cancer patients, accompanied by lipid droplet accumulation." (PMID 38906969, 2024). "Both CPT1A and CPT1B isoforms of CPT1 are now known to function as downstream target genes for PPARα regulation in many cancers." (PMID 39596847, 2024). "The majority of surveys have demonstrated that CPT1B exerts a pro-oncogenic function in a multitude of cancers; however, CPT1B also exhibits an oncogenic role in some cancer types." (PMID 39596847, 2024). "According to our data, ERRγ-regulated Cpt1b was responsible for facilitated FAO in chemoresistant cancer cells." (PMID 32206097, 2020). "Fasn is associated with cancer metabolism and was downregulated dramatically in SAHA/JQ1-treated cells, whereas Cpt1a and Cpt1b and the muscle differentiation factor Mef2c were elevated." (PMID 30382078, 2018). "This suggests that the overexpression of CPT1B leading to metabolic alterations may be a prerequisite for cancer cells’ growth and survival." (PMID 34181336, 2021). "Furthermore, targeting CPT1B in cancers with abnormal lipid metabolism and fatty acid oxidation (castration-resistant prostate cancer) is proposed." (PMID 34181336, 2021). "At the same time, ERRγ can facilitate FAO of chemoresistant cancer cells via upregulation of Cpt1b." (PMID 32206097, 2020). "Considering ERRγ cistromes may exhibit cell-type-specific features to match the metabolic profiles of individual cell types 17, the roles of ERRγ/Cpt1b axis-regulated metabolic reprogramming in chemoresistance of other cancers will need more studies." (PMID 32206097, 2020). "Multiple malignant tumors are characterized by the significant overexpression of FAO enzymes Carnitine Palmitoyltransferase 1A (CPT1A), Carnitine Palmitoyltransferase 1B (CPT1B), and Carnitine Palmitoyltransferase-2 (CPT2)." (PMID 41164182, 2025). "Studies have found that many of the key mediators of FAO, such as CD36, CPT1 (including CPT1A, CPT1B and CPT1C) and CPT2, are overexpressed in a variety of malignant tumors, and FAO has been found to be enhanced in a variety of cancers." (PMID 40514365, 2025). "ERRγ binds to p65 to upregulate ATP binding cassette subfamily B member 1 (ABCB1) and the rate‐limiting FAO enzyme carnitine palmitoyltransferase 1B (CPT1B), thereby enhancing FAO and drug resistance in cancer cells." (PMID 38721006, 2024). "We detected seven pairs of ccRCC tissues and corresponding para-carcinoma tissues and found a significantly lower level of ACADM and ACAT1 mRNA and a higher level of CPT1B and HACD1 mRNA in tumor tissues." (PMID 35873479, 2022). "Conclusions: m6A induced ERRγ confers chemoresistance of cancer cells through upregulation of ABCB1 and CPT1B." (PMID 32206097, 2020). "Our data suggest that ERRγ forms a complex with p65, binds CPT1B promoter to increase its expression, elevates FAO, and thus mediate chemoresistance of cancer cells." (PMID 32206097, 2020). "Moreover, cancer cells co-cultured with CRISPRa-modified adipocytes exhibited decreased FA uptake and reduced expression of FAO-related genes such as CD36 and CPT1B." (PMID 41345744, 2025).
cancer (continued). "Moreover, using RT–qPCR, we found in several CRISPRa conditions that the cancer cells had lower expression of both CD36, a fatty acid transporter on the cell membrane, and CPT1b, a key regulator of FAO in the mitochondria, further confirming decreased FAO." (PMID 39905264, 2025). "have found that the JAK/STAT3 pathway could control the expression of several genes involved in lipid metabolism, such as carnitine palmitoyltransferase 1B (CPT1B) and fatty acid β-oxidation (FAO), to mediate cancer stemness and chemoresistance." (PMID 40052129, 2025). "Increased FASN, CPT1B, and CD36 expression correlate with poor drug response in cancer patients." (PMID 35764645, 2022). "Our data showed that overexpression of Cpt1b significantly attenuated sh-ERRγ-increased sensitivity of Dox in HepG2/ADR cells, and also sh-ERRγ-downregulated ATP levels and FAO rate, suggesting that Cpt1b is involved in ERRγ-regulated FAO and chemoresistance of cancer cells." (PMID 32206097, 2020). "One study reported that increases in the m6A levels in ERRγ mRNA (estrogen receptor-related receptor) could trigger the splicing of precursor ESRRG mRNA to promote its expression, with the upregulation of ERRγ conferring chemoresistance to cancer cells through the upregulation of ABCB1 and CPT1B." (PMID 40000966, 2025). "Furthermore, they observed that expression of CPT1B and CPT2 was generally higher in the cancer cells, raising the possibility that increased CPT expression levels may contribute to perhexiline sensitivity." (PMID 37110858, 2023).
tumor (28 papers, 2013 to 2026). "Nuclear PFKM interacts with c-MYC, which upregulates the expression of carnitine o-palmitoyltransferase 1 muscle isoform (CPT1B) to activate FAO, thereby sustaining tumor cell survival upon glucose deficiency." (PMID 41818193, 2026). "We identified eight overexpressed and mutated tumor antigens with poor prognostic value of PRAD, including KLHL17, CPT1B, IQGAP3, LIME1, YJEFN3, KIAA1529, MSH5 and CELSR3." (PMID 34872584, 2021). "Carnitine palmitoyltransferase 1B (CPT1B) has been reported to be correlated with tumor proliferation and metastasis by regulating EMT in BLCA." (PMID 34706720, 2021). "Thus, our study unveils the novel MT1G/H3K14me3/CPT1B signaling axis, which drives lipid accumulation in ccRCC, promoting ccRCC tumor growth and metastasis." (PMID 38906969, 2024). "High m6A methylation level in drug-resistant cells can trigger the splicing of ESRRG precurser, increases the expression of CPT1B and induces up-regulation of ERRγ in chemoresistant cells, which can promote fatty acid oxidation of tumor cells and enhance chemoresistance of tumor cells." (PMID 35022030, 2022). "Fatty acid oxidation may affect tumor progression by affecting lymphangiogenesis, and CPT1B may participate." (PMID 33688464, 2021). "The researchers found that knocking down the expression of CPT1B in BLCA could increase the ability of tumor proliferation and invasion by inhibiting FAO." (PMID 33029112, 2020). "Moreover, CPT1C may be a key element of mitochondrial dysfunction-associated tumor cellular proliferation and senescence and functionally differs from the other three subtypes CPT1A, CPT1B and CPT2 11,12." (PMID 32641987, 2020). "The GEPIA web tool was used to depict the expression levels of CPT1s, including CPT1A, CPT1B and CPT1C, among different tumor stages in the TCGA cohort to evaluate the correlation between tumor stage and CPT1s expression." (PMID 37078750, 2023). "In this process, leptin, a secreted adipokine from adipocytes, has been reported to stimulate STAT3 and CPT1B by binding to the leptin receptor or PD-1 on CD8+ T cells, suppressing their glycolysis and anti-tumor ability." (PMID 34742349, 2021). "Meanwhile, RT-qPCR assays revealed that ALDH6A1, FBP1, HAO2 and PSAT1 were markedly under-expressed in tumor tissues in exceeding 60% cases, and that TYMP, HK3, P4HA3, IL4I1, CYP26A1 and CPT1B were over-expressed in tumor tissues in exceeding 70% cases." (PMID 32737333, 2020). "Accelerated tumor growth was accompanied by metabolic perturbations in CD8+ TILs that impaired their anti-tumor activity, including elevated STAT3 signaling, increased Cpt1b expression, and increased fatty acid oxidation at the expense of glycolysis." (PMID 34421889, 2021).
infection (11 papers, 2016 to 2025). The state of being infected such as from the introduction of a foreign agent such as serum, vaccine, antigenic substance or organism. "Similar to H19 overexpression though, silencing H19 expression also up‐regulated most of the genes involved in lipid breakdown, such as Acat2, Cpt1b, Ndafs4, Pck2, Cyp1a2, Acads and Atpsa1, at 72 hours after Ad‐H19 infection, although most of them were down‐regulated at 36 hours after infection." (PMID 31809000, 2020).
metabolic disorders (3 papers, 2017 to 2023). "As Cpt1b continues to develop as an intriguing target for the treatment of metabolic disorders, it is important to consider possible effects of varying dietary intake during such treatment." (PMID 29240830, 2017). "Therefore, our results suggest that UA may induce FA metabolic disorders via CPT1B-mediated mitochondrial transport." (PMID 36817129, 2023).
cardiovascular diseases (1 paper, 2025). "We selected top three proteins, Map7 domain-containing protein 1 (Map7D1) 17, Bcl-2-associated transcription factor 1 (Bclaf1) 18,19 and CPT1b 20,21, which were closely related to cardiovascular diseases, for further investigation." (PMID 40093901, 2025).